IRF7 (interferon regulatory factor 7)
Diseases named in the same sentence as IRF7 in open-access papers (continued):
Sharing a sentence is not in itself a finding about the gene and the disease.
cholangiocarcinoma (1 paper, 2024). A carcinoma that arises from the intrahepatic biliary tree (intrahepatic cholangiocarcinoma) or from the junction, or adjacent to the junction, of the right and left hepatic ducts (hilar cholangiocarcinoma). "Immunohistochemical results revealed that the expression of RIG-I, MAVS, cGAS, IRF3, MDA5, IFIT2, and IRF7 was significantly higher in liver tissue slices from patients with cholangiocarcinoma than in the control group." (PMID 38817870, 2024). "We analyzed the expression levels of Type I interferons and ISG genes in the tumor tissues of patients and normal control tissues, revealing a consistent upregulation of ISG genes, including ISG15, MX1, MDA5, IFIT2, IFIT3, IRF1 and IRF7, in the tumor tissues of patients with cholangiocarcinoma." (PMID 38817870, 2024).
chronic lymphocytic leukemia (1 paper, 2025). "MNDA interacts with chromatin and RNA polymerase II (Pol II) to control the transcription of genes such as IRF7, myeloid cell leukemia 1 (MCL1), and BCL2, enhancing type I IFN production and promoting apoptosis in leukocytes and chronic lymphocytic leukemia (CLL) cells." (PMID 40386782, 2025).
chronic obstructive pulmonary disease (1 paper, 2023). A chronic and progressive lung disorder characterized by the loss of elasticity of the bronchial tree and the air sacs, destruction of the air sacs wall, thickening of the bronchial wall, and mucous accumulation in the bronchial tree. "Besides, West Nile virus-infected peripheral blood mononuclear cells represent elevated levels of IFNs and IRF7 and increased oxidative stress, and rhinovirus infection facilitates oxidative stress and inflammation with increased IRF7 mRNA levels in chronic obstructive pulmonary disease." (PMID 36336986, 2023).
Cirrhosis (1 paper, 2021). A chronic disorder of the liver in which liver tissue becomes scarred and is partially replaced by regenerative nodules and fibrotic tissue resulting in loss of liver function. "Furthermore, genes typically expressed by monocytes/macrophages, CD14 and Irf7, were overexpressed throughout the course of liver injury with further elevation of CD14 in advanced cirrhosis compared to both inflammation and cirrhosis time points (P = 0.037 and P = 0.041, respectively)." (PMID 33858327, 2021).
cognitive decline (1 paper, 2018). "Recently, higher expression levels of IRF7 and type 1 interferon pathways were found to be associated with the aging brain, cognitive decline and neurodegeneration." (PMID 30385785, 2018).
Cryptosporidium infection (1 paper, 2022). "Given the importance of type I IFN signaling in defense against Cryptosporidium infection, further studies regarding Irf7 and the role of Nostrill in Irf7 regulation as a potential antiparasitic therapeutic may be warranted." (PMID 35464447, 2022).
demyelination diseases (1 paper, 2017). "Indeed, IRF7 is a significant regulatory factor in the development of demyelination diseases in the CNS, such as MS and EAE33, whereas IRF9 is important in injury-induced type 1 IRF signaling, which regulates inflammatory responses in the CNS50." (PMID 28747667, 2017).
E. coli infections (1 paper, 2024). "Different from E. coli infection, S. aureus infection induced IRF7 and phosphorylation of IRF7 through activating TRAF3‐IKKε/TBK1 axis, bypassing MyD88." (PMID 39166412, 2024). "IRF3 inactivation leads to the overexpression of IRF7, exacerbating kidney pathology in E. coli infections." (PMID 39166412, 2024).
epithelial dysplasia (1 paper, 2023). "Though not as pathological a phenotype as in the MyD88 KO, this reduced Md2 and Irf7 expression could contribute to MyD88-dependent dampened BAL infiltration and epithelial dysplasia in the Ffar4-null mice from our studies." (PMID 37108233, 2023).
Epstein-Barr virus infection (1 paper, 2021). An infection that is caused by Epstein-Barr virus. "Meanwhile, DEA unveiled that some enriched terms, such as regulation of defense (GO) and cytokine production (GO), Epstein-Barr virus infection (KEGG) and viral carcinogenesis (KEGG) were closely related to IRF7 expression (FDR ≤ 0.05)." (PMID 33805444, 2021).
esophageal cancer (1 paper, 2024). A primary or metastatic malignant neoplasm involving the esophagus. "In addition, overexpression of IRF2 promotes esophageal cancer cell proliferation and mutations of SNPs in genes such as IRF3, IRF5, and IRF7 may facilitate the progress of esophageal cancers, while IRF4 may be regarded as a protective factor in ESCC." (PMID 39384770, 2024).
essential thrombocythemia (1 paper, 2025). A chronic myeloproliferative neoplasm that involves primarily the megakaryocytic lineage. "The differential IRF7 responses in HEL (erythroblastic origin) and SET2 (megaloblastic origin) cells reflect the distinct inflammatory profiles of polycythemia vera (PV) and essential thrombocythemia (ET)." (PMID 40016346, 2025).
familial Mediterranean fever (1 paper, 2023). Familial Mediterranean fever (FMF) is an autoinflammatory disorder characterized by recurrent short episodes of fever and serositis resulting in pain in the abdomen, chest, joints and muscles. "We found: 1 H-P carries the likely pathogenic variant c.887-2 A>C in the IRF7 gene and 5 H-P carries variants in the MEFV gene, whose role in the pathogenicity of the familial Mediterranean fever (FMF) disease is controversial." (PMID 37760989, 2023).
Fever (1 paper, 2019). Body temperature elevated above the normal range. "The OROV fever pathogenesis was in fact described as restricted by the IFN pathway-related signaling molecules MAVS, IRF-3, IRF-7 in non-myeloid cells." (PMID 31784575, 2019).
fibrosarcoma (1 paper, 2022). A malignant mesenchymal fibroblastic neoplasm affecting the soft tissue and bone. "In fibrosarcoma cells, IRF3 and IRF7 mRNAs were detected, while IRF1 and MyD88 mRNAs were regulated." (PMID 35737804, 2022).
Flavivirus Infections (1 paper, 2021). Infections with viruses of the genus FLAVIVIRUS, family FLAVIVIRIDAE. "In particular, the critical contribution of IFN-I signal and transcription factors (IRF3, IRF5, IRF7, IPS-1, etc.)for IFN-I production to the control of in vivo flavivirus infection mostly focused on WNV has been described." (PMID 34130738, 2021). "Indeed, the critical role of IFN-I and its transcription factors (IRF3, IRF5, and IRF7) has been described in flavivirus infection in vivo including WNV and DenV, but not JEV." (PMID 34130738, 2021).
foot and mouth disease (1 paper, 2017). A viral infectious disease that results in infection in cattle and swine, has material basis in foot-and-mouth disease virus, which is transmitted by contaminated fomites, or transmitted by ingestion of food contaminated with infected meat or animal products. "Recently, Ramírez-Carvajal has demonstrated that a constitutively active fusion protein of porcine IRF3 and IRF7 completely protects swine against foot and mouth disease by inducing a strong type I IFN response." (PMID 28977918, 2017).
frontotemporal lobar degeneration (1 paper, 2020). "The IRF7 gene has been associated with frontotemporal lobar degeneration." (PMID 33329316, 2020).
Gall Bladder Carcinoma (1 paper, 2022). "A downregulation of IRF7 was also found in gall bladder cells, which is linked to low survival rates of gall bladder carcinoma patients." (PMID 35035811, 2022). "As downregulation of IRF7 is linked with low rates of survival, it was found that gall bladder carcinoma patients may face high mortality." (PMID 35035811, 2022).
Granuloma (1 paper, 2014). A compact, organized collection of mature mononuclear phagocytes, which may be but is not necessarily accompanied by accessory features such as necrosis. "Nevertheless, C. burnetii-induced granulomas were not only characterized by anti-inflammatory program; indeed, C. burnetii did induce several genes related to inflammation such as TNFSF13, CH25H, and IRF7 genes." (PMID 25566510, 2014).
Graves disease (1 paper, 2019). Graves' disease is an autoimmune disorder that leads to overactivity of the thyroid gland (hyperthyroidism).It is caused by an abnormal immune system response that causes the thyroid gland to produce too much thyroid hormones. "Our study has revealed for the first time that IRF7 is a susceptibility gene for AITD, especially for Graves' disease and Graves' ophthalmopathy." (PMID 30774658, 2019). "We selected three single nucleotide polymorphisms (SNPs) of IRF7, namely, rs1061501, rs1131665, and rs1061502 for genotyping using PCR-based ligase detection reaction (LDR) method in a total of 1659 participants (592 with Graves' disease, 297 with Hashimoto's thyroiditis, and 770 healthy controls)." (PMID 30774658, 2019).
Graves ophthalmopathy (1 paper, 2019). An autoimmune disorder of the EYE, occurring in patients with Graves disease. "Our results suggested the association of IRF7 polymorphisms with Graves' ophthalmopathy, thus adding IRF7 to the list of predisposing genes of Graves' ophthalmopathy." (PMID 30774658, 2019). "But according to our existing data, we cannot evaluate the association of IRF7 polymorphisms with the clinical activity, severity, and response to treatment of Graves' ophthalmopathy, which needs to be further studied in the future." (PMID 30774658, 2019).
hemorrhagic fever with renal syndrome (1 paper, 2020). A viral infectious disease that is a hemorrhagic fever, located_in kidney, has_material_basis_in Hantaan virus, has_material_basis_in Dobrava-Belgrade virus, has_material_basis_in Seoul virus, or has_material_basis_in Puumala virus, which are carried and transmitted_by rodents. "Notably, another study underscored that Hantaan virus, the pathogen of hemorrhagic fever with renal syndrome (HFRS), promotes the secretion of CXCL10 by facilitating NF-κB and IRF7 to directly bind to the promotor of CXCL10 in the downstream of MDA569." (PMID 32532953, 2020).
Herpes simplex infection (1 paper, 2022). "The KEGG pathway analysis highlighted that a large number of genes that were up-regulated after infection with V2 were the same as those upregulated in response to Herpes simplex infection (genes Myd88, Irf7, H2-Q7, Casp8, Tlr3, Daxx, C3, H2-Aa, Oas2, Oas3, H2-T22, H2-T23 and Cd74)." (PMID 35458422, 2022).
Hypercholesterolemia (1 paper, 2022). An increased concentration of cholesterol in the blood. "Furthermore, the regulatory network of PMs derived from hypercholesterolemia mice enclosed IRFs, including IRF3 and IRF7, that were highly connected to IFN-β and the affected biological processes." (PMID 35224060, 2022).
infarction (1 paper, 2018). A localised pathological necrosis of tissue resulting from obstruction of the blood supply usually by a thrombus, an embolus, or vascular torsion. "Moreover, Irf3 and Irf7 showed also an increased gene expression 5 days after infarction in the scar tissue." (PMID 29538462, 2018).
inflammatory bowel disease (1 paper, 2025). A spectrum of small and large bowel inflammatory diseases of unknown etiology. "In inflammatory bowel disease (IBD), IRF3 and IRF7 are upregulated in the intestinal mucosa, promoting localized inflammation." (PMID 41383611, 2025).
interstitial lung disease (1 paper, 2025). A diverse group of lung diseases that affect the lung parenchyma. "We previously demonstrated that interstitial lung disease developed largely independent of the IFN I signaling, and occurs in the absence of cGAS, IRF3, IRF7, and of IFNAR1." (PMID 40111902, 2025).
intrauterine growth restriction (1 paper, 2019). "Furthermore, vaginal inoculation of ZIKV early during pregnancy (at embryonic day 4.5) was associated with intrauterine growth restriction and fetal resorptions in WT females crossed with WT males, Ifnar1−/- females crossed with WT males, and IRF3−/-IRF7−/- females crossed with IRF3−/-IRF7−/- males." (PMID 31451049, 2019).
ischemia (1 paper, 2022). A hypoperfusion of the BLOOD through an organ or tissue caused by a PATHOLOGIC CONSTRICTION or obstruction of its BLOOD VESSELS, or an absence of BLOOD CIRCULATION. "This may be related to excessive use and requirement for interferon regulatory factor 7 in the acute phase of ischemia, which would be associated with its potential neuroprotective and proinflammatory function." (PMID 35268287, 2022).
ischemic cardiomyopathy (1 paper, 2022). Ischemic cardiomyopathy is a cardiomyopathy in which a weakness in the muscle of the heart due to inadequate oxygen delivery to the myocardium with coronary artery disease being the most common cause. "We identify a pro-fibrogenic macrophage subtype in non-ischemic cardiomyopathy, and demonstrate that WWP2 is a key regulator of IRF7-mediated Ccl5/Ly6chigh monocyte axis in heart fibrosis." (PMID 36450710, 2022).
ischemic stroke (1 paper, 2022). A stroke disorder caused by obstruction of blood flow to the brain, due to thrombotic (local blood clot formation) or embolic (due to a blood clot or other material traveling from another site) event. "There is only limited information available in the literature on the role of IRF-7 in ischemic stroke." (PMID 35268287, 2022).
kidney cancer (1 paper, 2023). Primary or metastatic malignant neoplasm involving the kidney. "IRF7 enhanced the proliferation and invasion of kidney cancer cells." (PMID 37251373, 2023).
liver cancer (1 paper, 2024). An epithelial or non-epithelial malignant neoplasm that arises from the liver. "The key functions of miRNA-146a-5p and IRF7 in aerobic glycolysis in liver cancer cells were determined through experiments analyzing glucose uptake, lactate production, the oxygen consumption rate (OCR) and the proton efflux rate (PER)." (PMID 39006088, 2024).
lung squamous cell cancer (1 paper, 2021). "However, Chang and colleagues showed that PD-L1 protein level is negatively correlated with IRF7 in lung squamous cell cancer tissues, which may result from the effect of PD-1/PD-L1 reverse signaling on eIF2α/ATF4 activation with subsequent downregulation of IRF7 expression." (PMID 34858816, 2021).
lymph node metastasis (1 paper, 2026). "Clinicopathological correlation analysis further showed that high RASSF1C expression was associated with poor differentiation and advanced TNM stage, whereas low UFL1 and IRF7 expression was associated with lymph node metastasis." (PMID 41912489, 2026).
memory impairment (1 paper, 2020). "Inducing ERV activation in the mouse brain causes significant hippocampus-related memory impairment accompanied by robust activation of antiviral immune response mediated through Irf7; the pathology is attenuated in mice lacking cytosolic viral RNA sensor protein MAVS." (PMID 33101276, 2020).
Meniere disease (1 paper, 2014). A disease of the inner ear (labyrinth) that is characterized by fluctuating sensorineural hearing loss; tinnitus; episodic vertigo; and aural fullness. "Nine proteins, including immunoglobulin and its variants and interferon regulatory factor 7, were found only in the inner ear fluid of patients with Meniere's disease." (PMID 25330336, 2014).
metastatic cancer (1 paper, 2023). A carcinoma which has spread from the original site of growth to another anatomic site. "This analysis showed that both mRNA and protein levels of CXCL10, CCl5 and IRF7 protein levels were elevated in metastatic cancer cells in culture and reduced in 66cl4-derived primary tumors." (PMID 36882786, 2023).
metastatic tumors (1 paper, 2024). "TempO-Seq analysis showed upregulation of innate immune response and IRF pathway genes (IRF1, IRF7, IFNAR2, JAK1, STAT1), yet no reduction was observed in the metastatic tumors." (PMID 38516270, 2024).
Mycobacterium infection (1 paper, 2023). Infections with bacteria of the genus Mycobacterium. "IRF7 promoted IFN-β expression and inhibited Mycobacterium infection." (PMID 37251373, 2023).
myeloid leukemia (1 paper, 2022). A clonal proliferation of myeloid cells and their precursors in the bone marrow, peripheral blood, and spleen. "Therefore, our findings uncover the intrinsic effects of IRF7 in AML and provide a potential strategy to control central nervous system myeloid leukemia." (PMID 35256780, 2022).
myocardial infarction (1 paper, 2018). Gross necrosis of the myocardium, as a result of interruption of the blood supply to the area, as in coronary thrombosis. "In this study, we observed highly increased gene expression levels of Tlr1, Tlr2, Tlr6, Tlr7, Tlr8, Tlr9 as well as Irf7 in the scar tissue after myocardial infarction, indicating their relevance to a proper cardiac wound healing." (PMID 29538462, 2018). "Interestingly, post myocardial infarction TLR and IRF gene expression was almost exclusively increased in the infarct zone after myocardial ischemia (Tlr2, Tlr3, Tlr6, Tlr7, Tlr9, Irf3, Irf7)." (PMID 29538462, 2018).
neuropathic pain (1 paper, 2019). Chronic pain caused by damage to nerve fibers. "Although no study linked IRF7 to neuropathic pain and other members of its family, an IRF8-IRF5 transcriptional axis may contribute to microglia activation in the neuropathic pain animal model through the P2X4R pathway." (PMID 30881521, 2019).
optic neuropathies (1 paper, 2026). "Interestingly, similar transcriptional suppression of interferon regulators like IRF7 has been observed in other optic neuropathies, which correlates with increased inflammasome activation and neuronal loss." (PMID 41601638, 2026).
ovarian tumor (1 paper, 2022). "In addition, ovarian tumor domain-containing 6B protein diminishes TRAF6-mediated K63-linked polyubiquitination of IRF3 and IRF7 to suppress IFN production." (PMID 36172355, 2022).
pancreatic adenocarcinoma (1 paper, 2024). "The study uncovered the mechanism by which IRF7 suppresses the growth of pancreatic adenocarcinoma cells." (PMID 39118300, 2024). "The main focus of this study is to explore the molecular mechanism of IRF7 regulation on RPS18 transcription in M1‐type macrophages in pancreatic adenocarcinoma (PAAD) tissue, as well as the transfer of RPS18 by IRF7 via exosomes to PAAD cells and the regulation of ILF3 expression." (PMID 39118300, 2024).
plague (1 paper, 2012). Plague is a severe bacterial infection caused by the gram-negative bacterium Yersinia pestis. "Similarly, 50% of Irf7−/− mice developed plague with a similar time to lethal disease." (PMID 22911267, 2012).
polycystic ovary syndrome (1 paper, 2023). A disorder that manifests as multiple cysts on the ovaries. "Toll-like receptor 4 mediates the activation of the IRF7/NF-κB pathway to aggravate inflammation in polycystic ovary syndrome." (PMID 36336986, 2023).
preeclampsia (1 paper, 2024). Preeclampsia is a hypertensive disorder of pregnancy that is characterized by new-onset hypertension with proteinuria presenting after 20 weeks of gestation, and depending on mild or severe forms may initially present with severe headache, visual disturbances, and hyperreflexia. "Notably, genes upregulated in preeclampsia and recurrent pregnancy loss were enriched with interferon pathway regulators IRF2 and IRF7, which promote NK cytotoxicity." (PMID 39090334, 2024). "Notably, the cell surface receptor CD2, which mediates nanotube formation and augments cytotoxicity, is a target of both IRF2 and IRF7 and was found to be upregulated in both preeclampsia and missed abortion." (PMID 39090334, 2024).
prostate tumors (1 paper, 2013). "This analysis revealed a prominent inverse correlation between uc.106 + A expression and the expression of many interferon pathway genes such as IRF7, ISG15, ISG20, OAS1-3, and PTPN22 in prostate tumors." (PMID 23409773, 2013).
respiratory syncytial virus infection (1 paper, 2016). "Cross-talk between oxidative stress pathways and IRF7 signaling was reported in the context of respiratory syncytial virus infection." (PMID 26810609, 2016).